HPRT1 (hypoxanthine phosphoribosyltransferase 1)
Description:
Converts guanine to guanosine monophosphate, and hypoxanthine to inosine monophosphate. Transfers the 5-phosphoribosyl group from 5-phosphoribosylpyrophosphate onto the purine. Plays a central role in the generation of purine nucleotides through the purine salvage pathway.
Synonyms: HGPRT; HPRT
Tractability: Small molecule: a structure with a bound ligand is known; a high-quality ligand is known; it has a high-quality binding pocket; it belongs to a druggable protein family. PROTAC: UniProt records ubiquitination sites on it; ubiquitination databases record sites on it; its protein half-life has been measured; a small molecule that binds it is known.
Target class: Enzyme; Transferase
Gene: Protein-coding gene on chromosome X (134,460,155 to 134,520,513, forward strand). Ensembl gene ENSG00000165704.
Subcellular location: Cytoplasm
Subcellular location (Human Protein Atlas): Cytosol; Annulus; End piece; Mid piece; Principal piece
Pathways (Reactome):
Disease: Defective HPRT1 disrupts guanine and hypoxanthine salvage
Drug ADME: Azathioprine ADME
Metabolism: Purine salvage
Gene Ontology:
Molecular function: guanine phosphoribosyltransferase activity; hypoxanthine phosphoribosyltransferase activity; identical protein binding; magnesium ion binding; protein binding
Biological process: GMP catabolic process; GMP salvage; guanine salvage; hypoxanthine metabolic process; hypoxanthine salvage; IMP metabolic process; positive regulation of dopamine metabolic process; protein homotetramerization; purine nucleotide biosynthetic process; purine ribonucleoside salvage; IMP salvage; AMP salvage
Cellular component: cytoplasm; cytosol; extracellular exosome
Gene-disease validity (ClinGen):
ClinGen rates the evidence that HPRT1 causes each of these diseases.
Lesch-Nyhan syndrome (X-linked): Definitive. Lesch-Nyhan syndrome (LNS) is the most severe form of hypoxanthine-guanine phosphoribosyltransferase (HPRT) deficiency, a hereditary disorder of purine metabolism, and is associated with uric acid overproduction (UAO), neurological troubles, and behavioral problems.
Homologues: Orthologues: chimpanzee HPRT1 (100% identical), macaque HPRT1 (100% identical), rabbit HPRT1 (98% identical), mouse Hprt1 (97% identical), guinea pig HPRT1 (96% identical), rat Hprt1 (95% identical), dog HPRT1 (94% identical), pig HPRT1 (94% identical), zebrafish hprt1 (91% identical), tropical clawed frog hprt1 (85% identical), Caenorhabditis elegans pgm-1 (21% identical), Drosophila melanogaster Pgm1 (20% identical). Paralogues in human: PRTFDC1 (67% identical), PGM2L1 (26% identical), PGM5 (24% identical), PGM2 (24% identical), PGM1 (21% identical), PGM3 (14% identical).
Diseases named in the same sentence as HPRT1 in open-access papers:
HPRT1 is named in the same sentence as 207 diseases in open-access papers, as found by Europe PMC text mining. Sharing a sentence is not in itself a finding about the gene and the disease. The quoted sentences say what the papers report.
Lesch-Nyhan syndrome (111 papers, 2005 to 2025). "Lesch–Nyhan disease (LND) is associated with a complete deficiency of hypoxanthine-guanine phosphoribosyltransferase (HPRT) activity due to mutations in the HPRT1 gene." (PMID 40710358, 2025). "There are probably other undiscovered factors other than the genotype at the HPRT1 locus, such as modifier genes and environmental factors that act in the phenotypic expression of the disease associated with HGprt deficiency." (PMID 40717738, 2025). "Lesch-Nyhan syndrome (LNS) is a rare X-linked recessive disorder caused by mutations in the hypoxanthine phosphoribosyltransferase 1 (HPRT1) gene, resulting in HPRT1 deficiency." (PMID 41416282, 2025). "Motor and cognitive disability and self-injurious behavior are hallmarks of Lesch-Nyhan syndrome (LNS) caused by mutations in Hypoxanthine Guanine Phosphoribosyltransferase (HPRT1), a key enzyme in the purine nucleotide salvage pathway." (PMID 39075237, 2024). "Lesch-Nyhan syndrome (OMIM phenotype number 300322) is an XLR condition due to an inactivating variant in HPRT1, resulting in hyperuricemia with subsequent intellectual disability, involuntary movements, self-injurious behavior, gout, and uric acid NL." (PMID 38606357, 2024). "Lesch-Nyhan disease (LND) is a severe neurological disorder caused by mutations in the HPRT1 gene, located on the X chromosome, that leads to the deficiency of hypoxanthine–guanine phosphoribosyltransferase (HGprt) enzyme." (PMID 38172668, 2024). "Hypoxanthine-guanine phosphoribosyltransferase (HGPRT) activity in transgenic flies expressing the wild-type or a Lesch–Nyhan disease (LND)-associated mutant form of human HPRT1." (PMID 38700995, 2024). "Two (case 12, 14) with hyperuricemia, AKI and obstructive stones at 2 and 10 months of life were found to have a pathogenic variant in the HPRT1 gene leading to the diagnosis of Lesch Nyhan syndrome." (PMID 37464296, 2023). "Lesch-Nyhan disease (LND) is a rare X-linked recessive disease caused by pathogenic mutations of the HPRT1 gene." (PMID 36601030, 2022). "For instance, Lesch-Nyhan syndrome is characterized by the accumulation of uric acid is caused by a mutation in the HPRT1 enzyme." (PMID 34299287, 2021). "Using homologous recombination, HPRT1 mutation is introduced in human ESCs which modeled Lesch-Nyhan syndrome and recapitulated the high rate of uric acid accumulation." (PMID 34299287, 2021). "Lesch-Nyhan disease (LND) is an inherited disorder caused by pathogenic variants in the HPRT1 gene, which encodes the purine recycling enzyme hypoxanthine–guanine phosphoribosyltransferase (HGprt)." (PMID 33875724, 2021). "An HPRT1 gene mutation is the cause of Lesch-Nyhan syndrome, which is an X-linked recessive disorder." (PMID 33584783, 2020). "This is the case of Lesch-Nyhan syndrome, in which the cells expressing the wild-type allele of HPRT1 reproduce faster, thus gradually causing decrease of the cells in which the mutant allele is expressed." (PMID 22280810, 2012). "Defects in HPRT1 have been widely associated with hereditary gout (such as Lesch-Nyhan syndrome)." (PMID 40508129, 2025). "In the context of Lesch-Nyhan syndrome, iPSC-derived neural models, including neural organoids, could serve as innovative platforms for studying the effects of HPRT1 variants and evaluating potential therapies." (PMID 40092560, 2025). "Data suggests that female carriers of inactivating variants in HPRT1 are usually asymptomatic but may have HPRT-related hyperuricemia or Lesch-Nyhan syndrome." (PMID 38606357, 2024). "Interestingly, the most severe human form of HPRT1 deficiency, known as Lesch-Nyhan’s syndrome and caused by HPRT1 mutations, is a neurological disorder characterized by hyperkinetic movements and by loss of dopamine in the basal ganglia." (PMID 38503737, 2024). "Indeed, rare genetic mutations in the HPRT1 gene, linked to Lesch-Nyhan syndrome, are known to lead to elevated xanthine levels and a concurrent reduction in cellular ATP70." (PMID 38503737, 2024).
Lesch-Nyhan syndrome (continued). "Lesch-Nyhan disease (LND: OMIM 3000322) is a rare neurogenetic disorder involving pathogenic variants in the HPRT1 gene encoding the enzyme hypoxanthine-guanine phosphoribosyltransferase (HGPRT)." (PMID 35559039, 2022). "Lesch-Nyhan disease is a rare X-linked neurodevelopemental metabolic disorder caused by a wide variety of mutations in the HPRT1 gene leading to a deficiency of the purine recycling enzyme hypoxanthine-guanine phosphoribosyltransferase (HGprt)." (PMID 25612837, 2015). "For instance, the knockout of Hprt exhibits no observable phenotypes in mice, whereas mutations in the human ortholog of Hprt, HPRT1, cause Lesch-Nyhan syndrome, whose symptoms include the overproduction of uric acid, nervous system impairment, and self-injurious behavior." (PMID 26301634, 2015). "Hprt1, or hypoxanthine phosphoribosyltransferase 1, is an enzyme involved in the generation of purine nucleotides through salvage, and mutations in the human ortholog of the Hprt1 gene are causal for Lesch–Nyhan syndrome, which presents with an array of neurological and cognitive phenotypes." (PMID 41451871, 2025). "This study identifies a novel variant in the HPRT1 gene (HPRT1:c.104C > T) associated with Lesch-Nyhan Syndrome (LNS), a rare genetic disorder that leads to severe neurological symptoms." (PMID 40092560, 2025). "This case report presents a Chinese patient with Lesch-Nyhan syndrome (LNS) who harbors a novel variant in the HPRT1 gene." (PMID 40092560, 2025). "Patients with Lesch-Nyhan syndrome (LNS) have disease-causing splicing mutations in the hypoxanthine-guanine phosphoribosyltransferase 1 (HPRT1) gene, which normally causes exclusion of exon 4, exon 5, and exon 6, respectively." (PMID 37909333, 2023). "We illustrate the utility of the model by prospective prediction and subsequent experimental validation on the functional consequences of missense variants in HPRT1 which may cause Lesch-Nyhan syndrome, and pinpoint the molecular mechanisms by which they cause disease." (PMID 37443362, 2023). "Lesch-Nyhan syndrome (LNS) is an X-linked disorder caused by mutations in the HPRT1 gene, coding for hypoxanthine-guanine phosphoribosyltransferase (HPRT)." (PMID 34121999, 2021). "Lesch–Nyhan Syndrome is a rare X-linked disease characterized by hyperuricemia, gout, dystonia, microcephaly, mental retardation, and self-injurious behavior, and is caused by the hypoxanthine-guanine phosphoribosyltransferase (HPRT1) enzyme deficiency and altered purine metabolism." (PMID 30060474, 2018). "Lesch-Nyhan syndrome (LNS), first reported in 1964, affects 1/380,000 live births and is due to mutations in the X-linked HPRT1 gene, resulting in defective hypoxanthine guanine phosphoribosyl (HPRT) transferase activity." (PMID 25923076, 2015). "The current studies focus on gene-editing to model Lesch–Nyhan disease (LND), which is caused by mutations in the HPRT1 gene." (PMID 41400570, 2025). "Lesch-Nyhan syndrome (LNS) is a rare X-linked disorder caused by hypoxanthine phosphoribosyltransferase 1 (HPRT1) gene mutations, leading to HPRT1 deficiency, hyperuricemia, and severe neurological dysfunction, including self-injurious behavior." (PMID 41416282, 2025). "Lesch–Nyhan disease (LND; OMIM 308000) is a X-linked recessive disorder associated with a defective hypoxanthine-guanine phosphoribosyltransferase (HPRT; EC 2.4.2.8) activity caused by pathogenic variants in the HPRT1 gene." (PMID 41398526, 2025). "Lesch-Nyhan syndrome (LNS, OMIM #300322) is a rare X-linked genetic disorder caused by variants in the HPRT1 gene, which codes for the Hypoxanthine-guanine phosphoribosyltransferase (HGPRT)." (PMID 40092560, 2025). "Among them, LAMP2, GRIA3, PHF6, and HPRT1 genes are associated with Danon disease, Intellectual deficiency, X-linked syndrome, Wu type, BFL syndrome, Lesch Nyhan syndrome and other syndromes." (PMID 38031145, 2023).
Lesch-Nyhan syndrome (continued). "The genetic dystonias were associated with the following genes: TOR1A, THAP1, SGCE, KMT2B, HPRT1 (Lesch Nyhan disease), PANK2 and GCDH (Glutaric Aciduria type 1)." (PMID 36445406, 2023). "A particular example of such offsetting activity is Lesch-Nyhan syndrome, which results from impaired activity of hypoxanthine phosphoribosyltransferase (HGPRTase), a necessary enzyme in the nucleotide salvage pathway encoded by the HPRT1 gene." (PMID 30622930, 2018). "Improved functionality of the combined system was demonstrated by targeted disruption of the HPRT1 gene to create isogenic disease models of Lesch-Nyhan-Syndrome." (PMID 24206569, 2013). "We created a model of Lesch-Nyhan syndrome by gene targeting of the HPRT1 gene (NM_000194), and a model of Fragile X syndrome by deriving a new HESC line from an affected blastocyst identified by preimplantation genetic diagnosis (PGD) to carry fragile X syndrome." (PMID 19137066, 2009). "Previously we have created a model for Lesch-Nyhan disease by gene targeting of the HPRT1 gene." (PMID 19137066, 2009). "We therefore selected hypoxanthine-guanine phosphoribosyltransferase-1 (HPRT1, Uniprot: P00492), an enzyme involved in the onset of Lesch-Nyhan disease and its attenuated variants, for a prospective study of the accuracy and utility of our model." (PMID 37443362, 2023). "For such a purpose, the Lesch-Nyhan disease (LND) has been selected as a valuable model to study the genetic-epigenetic interplay, especially to explore the epistasis between the housekeeping hypoxanthine phosphoribosyltransferase 1 (HPRT1) and β-amyloid precursor protein (APP) genes." (PMID 40717738, 2025). "In order to investigate whether neurons derived from HPRT1 mutant cell lines recapitulated disease phenotypes in vitro, as recently shown in case of patient-specific Lesch-Nyhan Syndrome (LNS) hiPSCs, wild-type and mutant cell lines were differentiated into central nervous system (CNS) neurons." (PMID 24206569, 2013).
hyperuricemia (33 papers, 2007 to 2025). An abnormally high level of uric acid. "HPRT-related hyperuricemia (OMIM phenotype number 300323) is an XLR condition due to an inactivating variant in HPRT1, resulting in hyperuricemia with subsequent gout and uric acid NL." (PMID 38606357, 2024). "Treatment for hyperuricemia in these conditions is like that of conditions associated with HPRT1 inactivating variants." (PMID 38606357, 2024). "For instance, deletion mutations in HPRT1 (hypoxanthine-phosphoribosyltransferase-1) can cause hyperuricemia, resulting in severe gout and acute renal failure (Kelley–Seegmiller syndrome)." (PMID 37714971, 2023). "HPRT1 gene variants disrupt normal purine metabolism, leading to the involvement of multiple organ systems, primarily characterized by hyperuricemia, dystonia, and neurological abnormalities, which makes LNS clinically heterogeneous and diagnostically challenging." (PMID 40092560, 2025). "Mutations in the HPRT1 gene can lead to either a complete or severe deficiency of the HGprt activity, which results in an accumulation of guanine and hypoxanthine that oxidize in uric acid leading to hyperuricemia and cause the LND or Lesch-Nyhan variants (LNVs, MIM: 300323), respectively." (PMID 40717738, 2025). "Therefore, inactivating variants in HPRT1 result in increased production of purines hypoxanthine and guanine and oxidation by XO to xanthine then uric acid with resultant hyperuricemia." (PMID 38606357, 2024). "Blood tests showed hyperuricemia and whole exome sequencing (WES) identified a novel hemizygous variant in the HPRT1 (NM-000194.3) gene: c.104T > C in exon 2, respectively." (PMID 40092560, 2025). "Thirteen participants were diagnosed with classic LND, on the basis of residual hypoxanthine‐guanine phosphoribosyltransferase enzyme activity, HPRT1 gene analysis, and/or the full clinical phenotype with hyperuricemia, dystonia, and self‐injurious behavior." (PMID 33689173, 2021). "The hypothesis that ALDH16A1 interacts with hypoxanthine-guanine phosphoribosyltransferase (HPRT1), which is implicated in the metabolism of uric acid and gout, was supported by the fact that the carriers of the variant present hyperuricemia." (PMID 37686694, 2023). "In infants and young children, increased renal clearance can effectively remove uric acid from the blood; therefore, there may be borderline hyperuricemia in HPRT1 disorders." (PMID 35559039, 2022). "Kidney stones and hyperuricemia suggested the diagnosis of LND, confirmed by absent erythrocyte HGprt activity and a HPRT1 c.222C>G; p.F74L pathogenic variant." (PMID 38653184, 2024).
gout (25 papers, 2007 to 2025). A condition characterized by painful swelling of the joints, which is caused by deposition of urate crystals. "The amyloid precursor protein (APP) is located on chromosome 21 and is linked to gout as a genetic risk factor for Alzheimer’s disease, which can induce disease through interaction with the mutated HPRT1." (PMID 38060535, 2023). "The HPRT1 gene, essential for purine metabolism, influences uric acid levels via its involvement in the purine salvage route; disturbances in this process may result in elevated uric acid synthesis, exacerbating an individual’s risk for gout." (PMID 39598418, 2024). "In this study, we found that the expression level of HPRT1 in the kidney tissue of gout model rats was significantly lower than that of the control group." (PMID 40508129, 2025). "The complicated relationship between the genes URAT1, GLUT9, ABCG2, HPRT1, XOR, and uricase shows the complex genetic framework that controls the metabolism of uric acid and the risk of gout." (PMID 39598418, 2024). "This suggests that the HPRT1 and CTSD proteins are key targets involved in the development of gouty arthritis, see." (PMID 40508129, 2025). "When exosomes from gouty arthritis rats were co-cultured with NRK cells, the protein expression of HPRT1 in NRK cells showed a significant downward trend compared to that in the normal rat plasma exosome treatment group." (PMID 40508129, 2025). "This further suggests that exosomes, via intercellular communication, influence the expression of HPRT1 and CTSD proteins in recipient cells, participating in the development and progression of gouty arthritis." (PMID 40508129, 2025). "Partial defects in HPRT1 enzymatic activity can lead to clinical symptoms such as HUA, urate kidney stones, and gout." (PMID 32308702, 2020).